Y_RNA (Y RNA )
Gene: Miscellaneous RNA gene on chromosome 20 (53,544,615 to 53,544,725, forward strand). Ensembl gene ENSG00000206959.
Homologues: Orthologues: macaque Y_RNA (94% identical), mouse Gm26329 (76% identical). Paralogues in human: Y_RNA (85% identical), Y_RNA (83% identical), RNY1 (82% identical), Y_RNA (82% identical), RNY1P5 (81% identical), Y_RNA (80% identical), RNY1P11 (79% identical), Y_RNA (79% identical), RNY1P16 (78% identical), RNY1P9 (78% identical), Y_RNA (78% identical), Y_RNA (77% identical), and 92 more.